FANCD2 (FA complementation group D2)
Diseases named in the same sentence as FANCD2 in open-access papers (continued):
Sharing a sentence is not in itself a finding about the gene and the disease.
tumor (120 papers, 2008 to 2026). "This was confirmed in the tumor RNA with homozygous alternate splicing of FANCD2 as a result of the mutation." (PMID 40072012, 2025). "We analyzed the tumor genomics, and used the data to define the effect the germline FANCD2 mutation had." (PMID 39768544, 2024). "On the other hand, the variant allele frequency (VAF) of this variant in the tumor was 0.26, indicating that one of the copies with the FANCD2 pathogenic variant was lost." (PMID 39768544, 2024). "High FA gene expression is typically associated with chemoresistance; the high level of FANCD2 expression is associated with reduced chemotherapy sensitivity and a higher tumor mutation rate." (PMID 39051418, 2024). "High expression of FANCD2 has significant association with T, N stage, pathologic stage, PR, ER status, molecular subtype, and tumor location (p < 0.05)." (PMID 36313179, 2022). "This implied a possible regulatory role of FANCD2 in the polarization of tumor-associated macrophages (TAMs)." (PMID 36267413, 2022). "More importantly, exciting novel findings from this study present new evidence linking the deficiencies of DNA damage repair genes (POLQ/FANCD2) with the activation of anti-tumor immunity through the cGAS-STING-STAT1 signaling pathway." (PMID 34206946, 2021). "We knocked out the FANCD2 gene and examined the functional impact of its loss on tumor growth and metastasis and performed assays for cell growth, cell cycle, and cellular localization." (PMID 32906798, 2020). "According to the big bang model, the FANCD2 mutation is a late mutation in this tumor, as otherwise, it would be equally distributed over all tumor areas." (PMID 28321501, 2017). "In case of FANCD2, the mutation bearing clones are predominantly located in comparatively small tumor areas (area 3, area 4, and focally in area 2)." (PMID 28321501, 2017). "To establish the importance of this previously uncharacterized variant of FANCD2, V2, we aimed to validate its role as a tumor suppressor." (PMID 28157704, 2017). "In response to DNA damage, FoxF1-deficient tumor cells showed significantly reduced FANCD2 monoubiquitination and FANCM phosphorylation, resulting in impaired formation of DNA repair foci." (PMID 26625197, 2016). "In both experiments there was a significant association between the presence of FANCD2 expression and tumour grade (p<2×10−16 and p<1×10−4 respectively)." (PMID 25071006, 2014). "The patient with a germline FANCD2 variant had a second hit in the tumor through chromosome 3 LOH." (PMID 40072012, 2025). "However, 2 patients with both BRCA2 and either FANCD2 or FANCE germline deleterious variants also had complex genomic tumor profiles with numerous copy number gains, losses, and copy-neutral LOH (CN-LOH) events." (PMID 40072012, 2025). "Genetic alterations in FANCD2 predominantly manifest as mutations, which are associated with overall survival, disease-specific survival, disease-free survival, and progression-free survival in certain tumor types." (PMID 38443946, 2024). "However, more cases, especially of tumor types that commonly benefit from PARPi, should be analyzed before judging FANCD2 pathogenic variants to be valuable biomarkers for this treatment." (PMID 39768544, 2024). "FANCD2 forms part of the Fanconi Anemia (FA) pathway, an uncommon heterogeneous biallelic genetic disorder characterized by progressive aplastic anemia, congenital growth malformations, and tumor susceptibility." (PMID 38814507, 2024). "Moreover, FANCD2 exhibits a strong correlation with infiltrating cell levels, immune checkpoint genes, tumor mutation burden (TMB), and microsatellite instability (MSI)." (PMID 38443946, 2024).
tumor (continued). "The presence of a FANCD2 mutation probably contributes to the potential initiation of the tumorigenesis process, also contributing to the progression of a pre-existing malignancy, thereby increasing the metastatic potential of a tumor." (PMID 39768544, 2024). "It stands to reason that, since FANCD2 is required for tumor survival and DNA ISL repair, patients with mutated FANCD2 might benefit from PARPi (PARP inhibitors)." (PMID 39768544, 2024). "Still, the presented evidence speaks of a possible influence of FANCD2 mutation on tumor processes." (PMID 39768544, 2024). "In addition, correlations between FANCD2 expression and the dryness index, tumor mutational burden, microsatellite instability (MSI), immune pathways, genes involved in iron metabolism, and sorafenib chemotherapeutic response were analyzed." (PMID 37821996, 2023). "FANCD2, an essential gene related to autophagy-dependent ferroptosis, could work as a biomarker, predicting the survival, chemotherapy sensitivity, tumor immunity, and mutation burden of LUAD." (PMID 35236309, 2022). "In our study, the high expression of FANCD2 group achieved a high fraction of neutrophil, which revealed that the ferroptosis-related gene FANCD2 might be closely associated with neutrophil-mediated tumor immunity." (PMID 35236309, 2022). "At the point of FGFR TKI-resistance, doubly mutated gene FANCD2 might be the driver of tumor re-sensitivity to the original cisplatin regimen." (PMID 32957974, 2020). "However, in one case, NGS showed a different mutation frequency of the FANCD2 mutation c.2734G > C (Substitution–coding) over the four tumor areas investigated which was confirmed by pyro-sequencing." (PMID 28321501, 2017). "Finally, CISD1, ATP5MC3, PGD, SLC7A11, ACSL3, and FANCD2 expression was confirmed to significantly correlate with tumor mutational burden (TMB), microsatellite instability (MSI), immune cell infiltration, cellular checkpoint dysfunction, and cancer sensitivity to drugs." (PMID 35320929, 2021). "Importantly, FANCD2 expression levels are strongly associated with tumour grade, revealing a potential exploitable therapeutic window to allow inhibition of the FA pathway in tumour cells, whilst sparing normal brain tissue." (PMID 25071006, 2014). "However, E6 and fancD2-deficiency accelerated E7-driven tumor development in K14E6E7 mice." (PMID 24086435, 2013). "There were seven distinct SNVs present in tumor DNA, with two of these also detected in the CaB34—NOTCH3 missense and FANCD2 synonymous mutation." (PMID 40497995, 2025). "These deleterious germline variants were monoallelic except for one patient with an underlying pathogenic germline FANCD2 variant with a second hit in the tumor due to chromosome 3 CN-LOH, leading to biallelic inactivation of FANCD2 in the tumor." (PMID 40072012, 2025). "HMGA1 recruits FANCD2 to protect stalled replication forks from degradation and assists with unwinding the R-loop, ultimately increasing the ability of tumor cells to cope with replication stress." (PMID 40288645, 2025). "Earlier research has indicated that FANCD2 has a function in controlling the tumour microenvironment and impacting its spread, growth, and programmed cell death." (PMID 39400935, 2024). "As a result, 2-DG had similar inhibitory effect on orthotopic tumor growth of FANCD2-KD, KMT2D-KO SCC23 cells and KMT2D-KO SCC23 cells." (PMID 39117659, 2024). "To further assess the impact of germinal FANCD2 and WNT10A mutations on the tumor, we conducted WES (whole exome sequencing) for the patient’s tumor sample." (PMID 39768544, 2024). "Based on our investigation utilizing the TCGA datasets, it was observed that the levels of FANCD2 expression in tumor tissues were notably elevated in comparison to their corresponding normal tissues." (PMID 38443946, 2024). "By utilizing the UALCAN database, we conducted an analysis comparing the levels of methylation in the FANCD2 gene between both healthy and tumorous tissues." (PMID 38443946, 2024).
tumor (continued). "We further knocked down FANCA and FANCD2 in DLD1-P cells to investigate if their depletions sensitize tumor cells to E7820." (PMID 38789724, 2024). "This independent function of FANCD2/FANCI is a crucial checkpoint for tumor cells as they disproportionately depend on the G2/M checkpoint to avoid mitotic disasters." (PMID 38443946, 2024). "The results demonstrated a positive correlation between FANCD2 and immune checkpoints in most tumor tissues, including CTLA4, HAVCR2, LAG3, PDCD1, PDCD1LG2, SIGLEC15, TIGIT, and particularly CD274." (PMID 38443946, 2024). "FANCD2 was positively correlated with the tumor proliferation signature pathway, DNA repair, and cellular response to hypoxia." (PMID 37821996, 2023). "The results suggested that FANCD2 silencing contributed to suppressing tumor growth and regulated ferroptosis-related genes." (PMID 36814203, 2023). "Pevonedistat significantly decreased the proportion of FANCD2+ cells compared to both control tumours (1.25% vs." (PMID 37226898, 2023). "Results from our analysis also indicate that, among the thirty genes which are differentially expressed in OSCCs, seven of them (namely BRCA1, CCNE2, CDC25C, CDK1, CDK2, E2F1, and FANCD2) positively correlate with both tumor grade and HPV infection." (PMID 36768994, 2023). "The expression of FANCD2 was positively correlated with the tumor proliferation signature, DNA repair, and cellular response to hypoxia." (PMID 37821996, 2023). "Four carriers of germline mutations had additional somatic DDR mutations in the primary tumor: ERCC4; BRCA1, ATM, FANCD2, and MLH1; BRCA1; and BRCA2, RAD50, and ATR." (PMID 36446793, 2022). "Thirty-six tumour-related genes including ALK, AR, BRCA2, FANCD2 and CBL were found to be mutated in all the three disease groups." (PMID 36686473, 2022). "Our research indicated that high expression of FANCD2 induced aberrant ferroptosis and further contributed to the abnormality of anti-tumor immunity in patients with LUAD." (PMID 35236309, 2022). "In summary, this is the first study to report that ncRNA-regulated FANCD2 in HCC plays a tumor-promoting role based on the starBase database, HCCDB, TIMER database, and GEPIA database, indicating that it can be employed as a potential prognostic marker." (PMID 36246623, 2022). "This study systematically analyzed the role of FANCD2 in tumor progression, prognosis, and therapy for patients with LUAD." (PMID 35646059, 2022). "Most FRGs with gain of CNV exhibited significantly higher expression in BCa tumor tissues compared to normal adjacent tumor tissues or normal bladder tissues, such as FANCD2, EMC2, and TFRC." (PMID 35386202, 2022). "FANCD2 expression levels were related to tumor-infiltrating immune cells and their matching gene signatures, including CD8+ T cells, natural killer (NK) cells, dendritic cells (DC), and Th2 cells in cases of LUAD." (PMID 35646059, 2022). "Subsequently, the relationship between FANCD2 expression and tumor-infiltrating lymphocytes (TILs) in GBM was also analyzed." (PMID 35754466, 2022). "According to the TCGA and GTEx databases, FANCD2 exhibited higher expression in 19 types of tumor tissues, including LUAD and LUSC, than in adjacent normal samples in the TCGA database." (PMID 35646059, 2022). "The relationships between FANCD2 expression levels and tumor-infiltrating immune cells and their equivalent gene signatures were analyzed using TIMER, GEPIA, TISIDB, and ssGSEA databases." (PMID 35646059, 2022). "When we examined the tumor immunity of FANCD2, we found that the FANCD2 expression level in HCC showed a significant interaction with immune infiltration." (PMID 36246623, 2022).
tumor (continued). "The results show that FANCD2 expression regulates the level of tumor-infiltrating immune cells through multiple pathways, which contributes to the formation of the immunosuppressive microenvironment." (PMID 35646059, 2022). "First, gathering more robust data or samples of HCC is needed to verify the tumor-promoting role of FANCD2." (PMID 36246623, 2022). "The Spearman correlation between FANCD2 expression and RNAss reached 0.56 (P < 2.2e-16), indicating FANCD2 plays a critical role in promoting tumor heterogeneity." (PMID 34434214, 2021). "Compared to studies on FANCD2′s involvement in the S phase, how FANCD2 plays specific roles in the M phase of a cell cycle and appears to underperformed, and these studies will certainly better our understanding of tumor cell division." (PMID 34884777, 2021). "When the coding gene of FANCD2 is knocked down, tumour cells are more likely to be damaged by ferroptosis." (PMID 34095228, 2021). "These all indicate the potential anti-tumor activation through a cGAS-STING-STAT1-mediated ISGs-involved pathway upon the loss of both POLQ and FANCD2 in ESCC." (PMID 34206946, 2021). "Our findings revealed that certain FRGs (CISD1, ATP5MC3, PGD, SLC7A11, ACSL3, and FANCD2) are significantly upregulated in LUAD and that their elevated expression is associated with both advanced tumor stage and unfavorable prognosis." (PMID 35320929, 2021). "Significant suppression of tumor growth was observed in FANCD2-KO cells, as compared to control cells in all three cell lines tested." (PMID 32906798, 2020). "We provide evidence of a novel role of FANCD2 in ESCC tumor progression and its potential usefulness as a biomarker for ESCC disease management." (PMID 32906798, 2020). "We showed by cell cycle analysis that the tumor-suppressive effect of FANCD2-KO in ESCC was mediated by suppression of cell proliferation through suppression of cell cycle progression." (PMID 32906798, 2020). "The combination of all data together showed a significant upregulation of FANCD2 RNA expression in ESCC tumor tissues (p = 0.01)." (PMID 32906798, 2020). "The temporal tumor with epithelioid morphology had multiple chromosomal losses, including at the FANCD2 locus, indicating chromosomal instability." (PMID 32014051, 2020). "We examined the gene expression levels of FOXM1 and FANCD2 in primary and recurrent tumor tissues in the NMIBC patient group." (PMID 32486251, 2020). "By reviewing the list of genes without impact like ERBB3, CASP8, RAF1 and KRAS (FaDu) as well as KEAP1, KRAS, RAF1 and FANCD2 (SAS), one finds tumor drivers ranked among the top 100 mutated genes in HNSCC." (PMID 29719593, 2018). "FANCD2, a marker of DNA repair foci co-localized with FoxF1 in nuclei of tumor cells treated with hydroxyurea, which induces a DNA-damage response." (PMID 26625197, 2016). "Marrow from 4-NQO treated tumor-bearing K14E7 Fancd2−/− or control 4-NQO treated K14E7 Fancd2+/+ mice was placed into LTBMC." (PMID 27637088, 2016). "FoxF1 co-localized with FANCD2 in nuclear foci of DNA-damaged tumor cells in vitro and in vivo, suggesting that FoxF1 plays a role in DNA repair via interaction with FA complex proteins." (PMID 26625197, 2016). "FANCD2 depletion strongly affects tumor development in vivo, clearly supporting the important role of a proficient FANC pathway in tumor progression and growth." (PMID 27827420, 2016). "FoxF1 co-localizes with FANCD2 in DNA repair foci in cultured cells and tumor tissues obtained from cisplatin-treated mice." (PMID 26625197, 2016). "Comparable data was obtained using a commercial tissue microarray, in which normal brain tissue was devoid of any FANCD2 expression, and expression was more prevalent with increasing tumour grade." (PMID 25071006, 2014). "We have recently developed an FA triple-staining immunofluorescence based method (FATSI) to evaluate FANCD2 foci formation in formalin fixed paraffin-embedded (FFPE) tumor samples." (PMID 25566506, 2014).
tumor (continued). "Despite their critical role in the cellular ICL response and their tumor suppressor function, very little is known about the structure, function, and regulation of the FANCD2 and FANCI proteins." (PMID 24278431, 2013). "IR-induced FANCD2 focus formation was also reduced in tumor specimens showing inducible PSMA1 knockdown." (PMID 24040035, 2013). "In contrast to tumor cells, down-regulation of TRF1 in FANCD2 cells is probably linked to the functional role of TFR1 in regulating cell cycle progression." (PMID 22980747, 2012). "Specifically, we show that phenylbutyrate inhibits the formation of FANCD2 nuclear foci after cisplatin treatment and this inhibition correlates to a down regulation of the tumor suppressor BRCA1." (PMID 18325101, 2008). "Overexpression of FANCD2 has been identified as a potential mechanism by which tumor cells may evade therapeutic intervention." (PMID 40415137, 2025). "This shift can support tumor growth and immune evasion, similar to FANCD2." (PMID 40415137, 2025). "Furthermore, TYRO3 has been demonstrated to inhibit ferroptosis, as well as FANCD2, thereby enhancing tumour cell survival." (PMID 40415137, 2025). "In this article, we describe a clinical case of a small PanNET, which demonstrated tumor progression accompanied by a germline FANCD2 mutation, previously not reported in PanNETs." (PMID 39768544, 2024). "It has been reported that FANCD2 can affect the immune microenvironment of tumours." (PMID 39400935, 2024). "An examination of the tumor specimen using scRNA-seq data may aid in predicting the effect of the therapy on FANCD2-mutant neuroendocrine cells as well." (PMID 39768544, 2024). "This might explain some of the risks connected with FANCD2 as an increase in Ki67 levels is universally connected with poor survival of tumor patients." (PMID 39768544, 2024). "Additionally, using the GEPIA2 tool, we integrated tumor expression data from TCGA and identified the top 100 genes significantly correlated with FANCD2 expression." (PMID 38443946, 2024). "Therefore, we used this criterion and identified four tumors with mutations in ERCC4, one tumor with mutation in ERCC1, two tumors with mutations in FANCD2 of which one also had a mutation in ERCC4 and one sample with a mutation in SPRTN." (PMID 38260495, 2024). "In this study, the FANCD2 variant was demonstrated to have an effect on tumor landscape compared to PanNETs without this mutation." (PMID 39768544, 2024). "However, to determine associations between FANCD2 and WNT10A germline mutations and clinical manifestation, e.g., response to therapy and prognosis or tumor molecular-level alterations, there is a need for a group of patients harboring variants in the gene." (PMID 39768544, 2024). "Besides, IHC assay confirmed the down-regulation of FANCD2 in tumor tissues of the Lv-shFANCD2 group than that in the Lv-shNC group." (PMID 36814203, 2023). "The role of FANCD2 was further explored in xenograft tumor mice models." (PMID 36814203, 2023). "Importantly, the precursor lesion, i.e., sex cords, segregated halfway between the naïve GCs from Fancd2+/+ mice and the late-stage tumour phenotype of the Fancd2−/− mice." (PMID 37174061, 2023). "The function of FANCD2 on cell viability, invasion, migration, and tumor growth were explored." (PMID 36814203, 2023). "We therefore hypothesised that pevonedistat will enhance the efficacy of carboplatin in combination with paclitaxel in RMC tumours by inhibiting the FANCD2‐mediated recruitment of XPF–ERCC1 to DNA ICLs induced by carboplatin." (PMID 37226898, 2023). "FANCD2 could be a promising biomarker for PAAD patients, and its strong correlation with PD-L1 and tumor microenvironment might serve as an underlying condition for personalized treatment." (PMID 37369808, 2023). "Currently different forms of FANCD2 are reported to have an oncogenic or tumor suppressive role." (PMID 36832225, 2023).